RN7SKP132 (RN7SK pseudogene 132)
Gene: Miscellaneous RNA gene on chromosome 10 (27,783,846 to 27,784,053, reverse strand). Ensembl gene ENSG00000251810.
Homologues: Orthologues: chimpanzee 7SK (72% identical), guinea pig 7SK (43% identical). Paralogues in human: RN7SKP173 (64% identical), RN7SKP133 (63% identical), RN7SKP10 (62% identical), RN7SKP189 (62% identical), RN7SKP217 (62% identical), RN7SKP180 (62% identical), RN7SKP243 (62% identical), RN7SKP273 (62% identical), RN7SKP50 (62% identical), RN7SKP65 (62% identical), RN7SKP102 (61% identical), RN7SKP124 (61% identical), and 284 more.